HMGA1 (high mobility group AT-hook 1)
Diseases named in the same sentence as HMGA1 in open-access papers (continued):
Sharing a sentence is not in itself a finding about the gene and the disease.
tumor (continued). "Here, we have discovered FOXM1 as a novel HMGA1-molecular partner, demonstrating that HMGA1 stabilizes FOXM1 in the nucleus preventing its degradation, increasing FOXM1-dependent transcriptional activity and potentiating its crucial role in tumour angiogenesis." (PMID 31311575, 2019). "Regarding gene expression reanalysis of TCGA EEC cohort, similarly to the results obtained in our initial set of samples, HMGA1 was significantly overexpressed in tumors from all stages when compared with the non-cancerous tumor-adjacent endometrial tissues." (PMID 31096664, 2019). "Furthermore, we found that HMGA1 and FOXM1 cooperatively promote the tumor angiogenic process in in vitro and in vivo models." (PMID 31311575, 2019). "Results of IHC analyses of DDX39A, HMGA1, HMGA2, HOXC9, and PBX1 expression in tumor samples." (PMID 31188873, 2019). "HMGA1 was highly expressed in HCC tumor samples compared with adjacent nontumor samples in our clinical dataset." (PMID 31340839, 2019). "All the authors agreed on reporting high levels of expression of both HMGA1 and HMGA2 in MDA-MB-231 cells, which have some properties of stem cells (self-renewal and invasion), while the property of metastasis is a specific characteristic of tumour cells." (PMID 29853899, 2018). "Both HMGA1 and NOTCH1 can act as oncogenes or tumour suppressors in a context-dependent manner." (PMID 29743479, 2018). "RT-PCR analysis confirmed the IHC data of DDLS and MLS expressing significantly higher level of HMGA1 mRNA than WDLS (P < 0.01), suggesting a role of the protein in the mechanism of tumor progression of in the highly aggressive and more de-differentiated LPS subtypes." (PMID 29980789, 2018). "To test whether Hmga1 compensates for Hmga2 in PDAC metastasis, we generated PDAC cell lines from tumours from KP172CT;Hmga2+/+ and KP172CT;Hmga2CK/CK mice (n = 4 each)." (PMID 30228296, 2018). "In human specimens, the downregulation of HMGA1, E2F1, and vimentin, analyzed by IHC, compared with the basal levels found in the biopsies revealed that trabectedin therapy reduces the mesenchymal markers of the tumor." (PMID 29980789, 2018). "The IHC analysis obtained from specimens derived from superior limb and parathyroid metastases of one patient whose tumor had progressed showed an increase of positive cells for HMGA1, E2F1, and vimentin supporting the role of HMGA1/E2F1 axis in MLS progression." (PMID 29980789, 2018). "Nevertheless it is evident that HMGA1 expression was higher in tumor tissues compared to normal while IL-24 was not detectable in tumor tissues independent of histology." (PMID 27602961, 2016). "In aggregate, these data suggest that HMGA1 and HMGA2 are expressed in non-overlapping tumor types, but are both associated with more aggressive phenotypes, and perhaps reduced patient survival." (PMID 26244988, 2015). "Although a growing body of evidences suggests the essential role of HMGA1 in tumor metastatic progression, we did not obtain the data for the correlation between HMGA1 expression and node metastasis in the tissue microarray." (PMID 25572132, 2015). "Neither Hmga1 nor Hmga2 were found to be expressed in virgin wild-type mammary tissue or ErbB2TG tumours analysed by qt-PCR." (PMID 23307470, 2013). "In RT–PCR mRNA study, HMGA1 and 2 mRNA expression was analysed on normal tissues from 7 organs (each organ sample pool included RNA from four normal tissues) and 31 tumours with 25 surrounding non-tumour tissues." (PMID 19156147, 2009). "In WNECs, the expression of HMGA1 and 2 was significantly higher in metastatic tumours than in tumours without metastasis (P<0.05, P<0.05; respectively)." (PMID 19156147, 2009). "In WNECs, the expression of HMGA1 and 2 was significantly higher in metastatic tumours than those without metastasis (P<0.05)." (PMID 19156147, 2009). "The average level of let-7 expression was lower in NETs with HMGA1 overexpression than in tumours with negative or moderate expression of HMGA1 (data not shown)." (PMID 19156147, 2009).
tumor (continued). "The observed aberrations are supposed to lead to an up-regulation of the HMGA1 gene in the affected tumours, as opposed to adult healthy tissues where HMGA gene expression is low or hardly measurable." (PMID 18651940, 2008). "Our results indicated that HMGA1 recruited FANCD2 to promote DNA replication and cell cycle progression both by attenuating R-loop-induced replication stress and by protecting stalled replication forks from degradation, ultimately enhancing tumor resistance to chemotherapy and irradiation treatment." (PMID 40288645, 2025). "Besides, at the high-resolution dataset, compared with other four genes, HMGA1 showed the most significant negative correlation with T cell inflamed and positive with tumor cells." (PMID 38329444, 2024). "Moreover, KPC mice with loss of a single Hmga1 allele within pancreatic ductal epithelium exhibit increased tumor latency, less fibrosis, and decreased FGF15 immunoreactivity, further supporting a collaborative role for HMGA1 and FGF15 in tumorigenesis and fibrotic desmoplasia." (PMID 36919699, 2023). "Using publicly available data, HMGA1 was shown to be overexpressed in both small and non-small lung tumors, with higher expression compared to both the adjacent non-malignant lung tissues and non-tumor lung tissues of healthy individuals." (PMID 35805937, 2022). "MiR-26 has been proven to be a multiple tumour suppressor; it does not control IL-6-related inflammation and tumour promoting activity through transcription inhibition but downregulates the production of IL-6 through HMGA1 and MALT1 silencing-induced NF-κB inhibition." (PMID 35864955, 2022). "Notably, HMGA1 is a positive regulator of the IGFs system, with its own DNA binding sites within the IGFBP1 gene promoter, and it is also an inducer of matrix metalloproteinases and other genes involved in tumor invasion." (PMID 36506071, 2022). "Considering only the cases with high expression of HMGA1 detected in stages III and IV, where the significant and most striking differences were obtained in mean OS values, our data supports the selection of 40% of the GC patients diagnosed in all tumor stages, except stage I, for treatment." (PMID 35049679, 2021). "This positive feedback effect of HMGA1-c-Myc nexus may not just suit pCCA, but also adjust other kinds of tumors, which could be a common molecular feature of tumor cells." (PMID 33648560, 2021). "These experiments also helped to show that BP-1-102 treatment represses HMGA1, highlighting that not only does HMGA1 induce STAT3 expression but even STAT3 feeds forward to upregulate HMGA1, leading to an enhanced expression of both genes during tumor progression." (PMID 32503270, 2020). "We, therefore, asked whether HMGA1 and FOXM1 are involved in tumor angiogenesis." (PMID 31311575, 2019). "Furthermore, conversely to HMGB1, HMGA1 is not released from apoptotic tumor cells, and its secretion clearly correlates with an invasive phenotype in TNBC cells." (PMID 31779212, 2019). "In order to explore any disease relevance connecting HMGA1 and HMGA2 expression and tumor phenotype, we stained CRC tumor tissue arrays for these proteins and evaluated expression in relationship to various parameters including tumor stage, histopathologic characteristics, and disease outcomes." (PMID 26244988, 2015). "Thus, the overexpression of HMGA1 and HMGA2 may be involved in the carcinogenesis and progression of RMS, and these two genes may also be prognostic indicators of the tumor and provide a new basis for targeted therapy." (PMID 24743780, 2014). "The results indicated that HMGA1 depletion did not significantly affect tumour growth (left)." (PMID 23945276, 2013).
tumor (continued). "However, several tumor types with positive correlations (e.g., GBMLGG, LGG, and SARC) are known to harbor immunosuppressive infiltrates, suggesting that HMGA1 may be linked to dysfunctional rather than effective immune presence." (PMID 41463532, 2025). "In fact, HMGA1 itself does not have transcriptional activity, which may be because its protein chaperones or regulated genes varies according to cell microenvironment and tumor heterogeneity." (PMID 35864955, 2022). "Indeed, HMGA1 proteins are the most abundant nonhistone, chromatin-binding proteins in tumor cells." (PMID 32503270, 2020). "The first clue was provided by the finding that sequences in the 3′UTR of both HMGA1 and HMGA2 mRNAs could negatively control the expression of these mRNAs, whereas the deletion of these sequences—mimicking cytogenetic aberrations found in human tumours—led to protein overexpression." (PMID 31979076, 2020). "However, a mechanistic explanation of how extracellular HMGA1 could impact tumor invasion is not yet known." (PMID 31779212, 2019). "However, we could not rule out that HMGA1 also binds to other receptors, such as Toll-like receptors (TLRs) in tumor cells." (PMID 31779212, 2019). "However, there is no obvious relationship between the HMGA-1 and tumor regrowth." (PMID 28255749, 2017). "However, it is to be noted that in both cell lines and tumours, data showed a trend that was not statistically significant given the low number of samples analysed and the huge heterogeneity of expression shown by HMGA1, FOS and MYC in tumors." (PMID 22363436, 2012). "High-mobility group AT-hook 1 (HMGA1) is a non-histone, chromatin-binding protein that has been found overexpressed in several tumor types." (PMID 35049679, 2021). "Xenografts were established with HMGA1-overexpressing stable cells with or without TRIP13 knockdown, showing that TRIP13 knockdown significantly reduced tumor volume and weight which were increased by HMGA1 overexpression." (PMID 33648560, 2021). "There was a significant negative correlation between HMGA1 and HEYL in the majority of tumour types analysed and a particularly strong anti-correlation in lung SCC (R = −0.4842; p = < 0.0001)." (PMID 29743479, 2018). "To determine whether HMGA1 and FGF19 are relevant in human PDAC, we queried published data sets (GSE15471; n = 36 nonmalignant tissue, n = 36 tumor samples)." (PMID 36919699, 2023). "Thus, in our study we investigated the expression levels of HMGA1, HMGA2, Lin28, let-7 a and mir-98 via relative real time PCR in human and canine non-neoplastic and tumour tissue samples and human and canine cell lines which derived from primary OSCCs." (PMID 25245141, 2014). "However, we could not discard a danger signal triggered by HMGA1 in the tumor microenvironment, and future studies are needed to determine whether extracellular HMGA1 binds to other receptors beyond RAGE either in tumor or stromal cells." (PMID 31779212, 2019).
adenocarcinoma (8 papers, 2009 to 2024). A common cancer characterized by the presence of malignant glandular cells. "For adenocarcinoma, a connection between HMGA1 expression level and overall survival was detected with Cox p-value < 0.1 in nine of fourteen different datasets, and between HMGA1 expression and relapse-free survival in one of two datasets." (PMID 35805937, 2022). "HMGA1 activates the RAD51 promoter through two response elements, promoting radiation resistance, while its knockdown sensitizes clear cell adenocarcinoma cells to X‐ray exposure." (PMID 39690136, 2024). "In fact, increasing HMGA1 levels were observed going from low- to high-grade dysplasia (HGD) and adenocarcinoma." (PMID 25859543, 2015). "HMGA1 and HMGA2 evaluation in esophageal carcinoma revealed interesting differences between adenocarcinoma and squamous histotypes." (PMID 25859543, 2015). "HMGA1 was not expressed in normal epithelium surface where adenocarcinomas originated, but it was highly expressed in invasive ovarian carcinomas, and weakly expressed in ovarian carcinomas with low invasive potential." (PMID 25859543, 2015). "We could not find any significant differences in HMGA1 and 2 expression between PNEC areas and adenocarcinoma areas in several PNEC cases (data not shown)." (PMID 19156147, 2009).
metabolic disease (6 papers, 2014 to 2025). A congenital disorder (due to inherited enzyme abnormality) or acquired (due to failure of a metabolically important organ) disorder resulting from an abnormal metabolic process. "In addition, they further support the notion that HMGA1 is an architectural element tightly linked to glucose metabolism and metabolic disorders." (PMID 25628604, 2014). "In metabolic diseases, HMGA1 regulates insulin signaling pathways, affecting insulin sensitivity and glucose metabolism homeostasis." (PMID 39507236, 2024).
cardiovascular diseases (5 papers, 2015 to 2022). "There is increasing evidence that HMGA1 protein plays a vital part in the development and progression of a plenty of cardiovascular diseases 16-18,21." (PMID 32398950, 2020). "High-mobility group A1 (HMGA1) acts as a transcription factor in several cardiovascular diseases." (PMID 34513822, 2021).
infection (4 papers, 2016 to 2025). The state of being infected such as from the introduction of a foreign agent such as serum, vaccine, antigenic substance or organism. "Both the knockdown of HMGA1 protein expression and the inhibition of HMGA1 activity using the chemical inhibitor Netropsin uniformly exacerbated the DNA damage caused by BoHV-1 productive infection." (PMID 39769030, 2024). "As infection with HBS virus exhibited the largest reduction of HMGA1 protein levels and caused significantly more cell death than the other viruses, we concluded that sequestration of HMGA1 protein had a higher impact on suppressing HMGA1 oncogenesis than blocking new synthesis of HMGA1." (PMID 41183073, 2025). "Overall, these results suggest that BoHV-1 productive infection promotes the nuclear accumulation of HMGA1." (PMID 39769030, 2024). "We observed that BoHV-1 productive infection in MDBK cells resulted in increased HMGA1 protein expression at 12 and 24 h post-infection, which corroborates our previous findings." (PMID 39769030, 2024). "In conclusion, these data imply that HMGA1 may play a significant role in mitigating DNA damage following BoHV-1 productive infection." (PMID 39769030, 2024). "By focusing on the two macrophage states detected 8 h after the infection, we found the first state to be characterized by the module containing Irf7, Hmga1, Zfp275, and Stat1 that has been previously shown to initiate the inflammatory response to pathogens in an interferon gamma dependent manner." (PMID 34404761, 2021). "Given that BoHV-1 productive infection in cell cultures leads to overproduction of DSBs, which may consequently lead to cell death and is detrimental to viral replication, we wondered whether HMGA1 plays a crucial role in countering the DNA damage induced by BoHV-1 infection." (PMID 39769030, 2024). "To evaluate the role of HMGA1 protein in BoHV-1-induced DNA damage, we initially monitored its expression in MDBK cells infected with BoHV-1 at a multiplicity of infection (MOI) of 1 over various time points." (PMID 39769030, 2024).
gastrointestinal tumors (2 papers, 2019 to 2022). "Interestingly, HMGA1 displays a critical role in the detection and progression of gastrointestinal tumors." (PMID 35692504, 2022). "Additionally, it has also been reported that HMGA1 and HMGA2 possess an important biomarker potential for the detection and progression of gastrointestinal (GI) tumors." (PMID 31737655, 2019). "Additionally, it has also been reported that HMGA1 and HMGA2 display an important role in the detection and progression of GI tumors." (PMID 31737655, 2019).
hematologic malignancies (2 papers, 2016 to 2020). "In particular, HMGA1 is overexpressed in several high-grade or refractory neoplasias, including hematologic malignancies and solid tumors." (PMID 32503270, 2020). "The inhibition of Egr1, Hmga1 and Zfp36l2 transcripts was also related to hematological disease by IPA analysis, especially defects in erythropoiesis in CPF and ETU." (PMID 27905518, 2016).
HMGA1 also shares sentences with these, for which no sentence is quoted: atherosclerosis (5 papers); Hypercholesterolemia (4); teratoma (4); chronic myelogenous leukemia (3); small cell lung carcinoma (3); yolk sac tumor (3); B cell lymphomas (2); brain tumor (2); coronary artery disease (2); Endometrioid Endometrial Carcinoma (2); endometriosis (2); hyperlipidemia (2); Hypoinsulinemia (2); pancreatic ductal adenocarcinoma (2); polyposis (2); pulmonary hypertension (2); thyroid follicular cancer (2); uterine cancer (2); acute lung injury (1); acute myeloid leukemia (1); adenosarcoma (1); angiosarcoma (1); B-cell neoplasm (1); benign tumors (1); bladder tumor (1); bronchitis (1); diffuse astrocytoma (1); ductal carcinoma in situ (1); endometrial polyp (1); erythrocytosis (1).
A further 47 diseases each share a sentence with HMGA1 in 1 paper.